TH (tyrosine hydroxylase)
Diseases named in the same sentence as TH in open-access papers (continued):
Sharing a sentence is not in itself a finding about the gene and the disease.
Parkinson disease (continued). "HPA can be treated by Phe-deficient diet and the intellectual disabilities and parkinsonism are ameliorated by treatment with direct precursors for serotonin and dopamine, thereby circumventing the activities of TPH2 and TH, respectively." (PMID 39695187, 2024). "A decrease in TH immunoreactivity is a common feature of neurodegenerative diseases like Parkinson’s disease, in which there is a reduction in dopamine production." (PMID 39000030, 2024). "The dopaminergic signaling pathway was upregulated through exercise training in different animal strains of Parkinson’s disease, which increased striatal tyrosine hydroxylase (TH) protein expression and dopamine (DA) levels." (PMID 39844853, 2024). "This study underscores the therapeutic potential of enhancing tyrosine hydroxylase Ser40 phosphorylation to improve motor function in Parkinson’s disease." (PMID 39456033, 2024). "For instance, researchers have utilized CRISPR/Cas9 to create a tyrosine hydroxylase (TH) reporter hiPSC line for live imaging and isolation of dopaminergic neurons for the study of Parkinson disease." (PMID 39456792, 2024). "TH expression was significantly reduced in the substantia nigra and striatum of Parkinson’s mice (p < 0.05), while Iba-1 expression was elevated (p < 0.05)." (PMID 38398662, 2024). "In this study, we sought to explore cyclic nucleotide-mediated tyrosine hydroxylase Ser40 phosphorylation as feasible therapeutic approach for addressing the motor symptoms in Parkinson’s disease." (PMID 39456033, 2024). "In model cells with reduced dopamine levels in Parkinson’s disease models or reduced biopterin levels in dopa-responsive dystonia, the phosphorylation level of TH increases, and over time, the TH level decreases." (PMID 38069360, 2023). "In this context, in Parkinson’s disease model cells treated with a proteasome inhibitor, the TH protein forms insoluble aggregates." (PMID 38069360, 2023). "Tyrosine hydroxylase is the rate-limiting enzyme of dopamine synthesis and shows dysregulation and degradation in Parkinson’s disease." (PMID 37270842, 2023). "It has been shown that exposure to continuous bright light can reduce tyrosine hydroxylase (TH)-positive dopamine neurons and thus influence the prevalence of Parkinson’s disease." (PMID 37237884, 2023). "As mentioned in the previous section, the activation of the TH protein by its phosphorylation accelerates its degradation in Parkinson’s disease model cells as well as the dopa-responsive dystonia model." (PMID 38069360, 2023). "At the level of the SNpc, the TH+ cell death and the neuronal soma volume were measured as hallmarks of the neurodegenerative process induced by the experimental model of parkinsonism." (PMID 36995433, 2023). "In Parkinson’s disease and dopa-responsive dystonia, the TH protein in the substantia nigra striatum is lost." (PMID 38069360, 2023). "Tyrosine hydroxylase (TH), the rate-limiting enzyme responsible for dopamine synthesis, is used as a marker of dopaminergic neuronal integrity in Parkinson’s disease models." (PMID 37388445, 2023). "Reduced TH expression can result in a decline in DA synthesis that ultimately leads to parkinsonism." (PMID 37452461, 2023). "There were differences in the contents of tyrosine hydroxylase in left and right brain hemispheres of control and Parkinson’s disease model mice." (PMID 36091443, 2022). "In an MPTP mouse model of Parkinson’s disease, it was found that intraperitoneal application of capsaicin (0.5 mg/kg) increased the number of dopaminergic (tyrosine hydroxylase positive) neurons in the substantia nigra." (PMID 35458680, 2022). "NLC treatment increased GDNF levels, restored motor activity, increased TH expression, and modulated the microgliosis present in a model of Parkinson’s disease." (PMID 35300705, 2022). "We also stained for tyrosine hydroxylase (TH), a marker of dopaminergic neurons in the substantia nigra that are degenerated in Parkinson’s disease." (PMID 35404932, 2022).
Parkinson disease (continued). "The survival of tyrosine hydroxylase-positive neurons is one of the critical signatures in the development of Parkinson’s disease." (PMID 36235835, 2022). "In an in vivo experiment, using deer antler extract to treat a rat model of Parkinson’s disease, the death of tyrosine hydroxylase-positive neurons was significantly inhibited." (PMID 36235835, 2022). "In line with this, tyrosine hydroxylase (TH)-positive enteric dopaminergic neurons gained increased interest to understand GI dysfunctions in Parkinson’s disease." (PMID 34440476, 2021). "Partial microglial depletion rarely impacted the process of Parkinson's disease, indicated by the levels of TH proteins in the substantia nigra and the striatum, striatal TH+ fibre density and neurotransmitters, and motor functions." (PMID 34312932, 2021). "Parkinson’s disease is characterized with progressive degeneration of dopaminergic neurons, where tyrosine hydroxylase (TH) catalyzes the formation of L-dihydroxyphenylalanine (L-DOPA) as the rate-limiting step in the biosynthesis of DA." (PMID 32836217, 2020). "If gene therapy is ever to be considered as a treatment for Parkinson’s disease, we will have to find a way to meaningfully increase TH-positive terminals in the striatum, as motor benefits are primarily dependent on TH expression in the putamen." (PMID 32203581, 2020). "A study of Parkinson’s disease demonstrated that overexpressed TNF can reduce the expression of tyrosine hydroxylase (TH) and that TNF is toxic to catecholaminergic neurons." (PMID 32145751, 2020). "Tyrosine hydroxylase expression in the striatum is reported to be low due to reduced dopamine observed in most Parkinson’s disease patients." (PMID 32533070, 2020). "This contrasts with delivery to putamen alone where only 37.57% (right nigra) and 41.04% (left nigra) of remaining melanized neurons displayed TH-positivity, a number similar to that seen in untreated Parkinson’s disease cases (49.92%)." (PMID 32203581, 2020). "It has been demonstrated that in mice, the level of PITX3 expression correlates with TH+ mDA neurons and this in turn correlates with greater sensitivity of neurons to degeneration in Parkinson’s disease (PD)." (PMID 32825046, 2020). "Neuroprotection in the 6-OHDA model of Parkinson’s disease is characterized by the prevention of TH+ neuron death and the normalization of DA content in the striatum and movement activity." (PMID 31745133, 2019). "We next evaluated dopaminergic neurons responsible for motor control and important in Parkinson’s disease by quantifying the tyrosine hydroxylase marker." (PMID 31140977, 2019). "The PPM3 cluster has been shown to have fewer TH+ neurons in Drosophila models of Parkinson’s disease." (PMID 29898654, 2018). "Neuroprotective role of Spirulina is also marked in alpha-synuclein model of Parkinson’s disease, where increased expression of tyrosine hydroxylase (TH) positive and NeuN positive cells was observed." (PMID 30618587, 2018). "AGME treatment ranging from 125 to 375 mg/kg BW in a mouse model of Parkinson’s disease gradually increased the abundance of TH-positive cells compared with the NSS + MPTP treatment group." (PMID 29558946, 2018). "In order to evaluate effects of antibody treatment on Parkinson’s disease-like toxicity, levels of catecholamines were measured by immunohistochemistry with Tyrosine Hydroxylase (TH) in the olfactory bulb, substantia nigra, striatum and locus coeruleus." (PMID 29544548, 2018). "This is in agreement with previous studies where 3,4-DHPA, at similar doses (20 μM), completely blocked the effect of peroxynitrite on tyrosine hydroxylase, an enzyme involved in Parkinson’s disease pathology." (PMID 28352628, 2017). "For example, acupuncture at GB34 and LR3 acupoints attenuates the decrease of tyrosine hydroxylase and exhibits the protective effects via affecting the expression of degeneration-related genes in the substantia nigra region in Parkinsonism mouse model." (PMID 28810910, 2017).
Parkinson disease (continued). "PC—12 cell, a monoamine cell derived from pheochromocytoma of the male rat adrenal medulla which expresses Tyrosine hydroxylase (TH) and synthesise dopamine inside of cell, is widely used to study Parkinson’s disease model in vitro." (PMID 26894626, 2016). "In rotenone-induced mouse model of parkinsonism, ALDH2 activation using Alda-1 also attenuates rotenone-induced loss of SN TH+ dopaminergic neurons in mice." (PMID 25263579, 2015). "To further verify the role of nigral FA1/dlk1-ir cells we performed immunohistochemical analyses of FA1/dlk1 and TH in brain sections from 6-OHDA-lesioned rats (experimental model of Parkinson’s disease)." (PMID 25723595, 2015). "TH activity is important for dopamine synthesis in the brain, and dysregulation of TH activity contributes to Parkinson’s disease." (PMID 24690920, 2014). "We have introduced a planarian model of parkinsonism in which pharmacological inhibition of TH, the first and rate-limiting enzyme of DA biosynthesis, by MIT is used." (PMID 24287905, 2013). "We report the implementation and preliminary validation of planarian parkinsonism through TH inhibition in an experimental setup based on the organism’s anti-tropism to light." (PMID 24287905, 2013). "In conclusion, here we reported the ability for p73 to regulate tyrosine hydroxylase and by doing this, protecting against events that can lead to Parkinson disease." (PMID 23271007, 2012). "Tyrosine hydroxylase is a crucial player in Parkinson disease being the enzyme necessary for dopamine synthesis." (PMID 23271007, 2012). "However, there is no information available about whether human albumin can prevent loss of tyrosine hydroxylase (TH) expression of dopaminergic (DA) neurons induced by 6-hydroxydopamine (6-OHDA) toxicity that is most commonly used to create a rat model of Parkinson's disease (PD)." (PMID 22815976, 2012). "We also demonstrate that p73 can protect against tyrosine hydroxylase depletion in an in vitro model of Parkinson disease." (PMID 23271007, 2012). "Ex-vivo brain tissue was analyzed for changes in tyrosine hydroxylase staining as a biomarker for Parkinson's disease severity." (PMID 22316420, 2012). "In our study, following the rotenone infusion in the MFB of the rats, the Parkinson's disease state was defined as TH immunostaining in the striatum with a density of less than 40% of control values (termed responders)." (PMID 22316420, 2012). "Reduction of dopaminergic neurons in PD patients and animal models of parkinsonism leads to substantial loss of the pre-synaptic markers DAT, TH and VMAT2." (PMID 22359591, 2012). "Parkinson's disease-like pathology, indicated by a huge reduction of tyrosine hydroxylase as well as by substantially reduced levels and higher elimination rates of DOPAC and HVA, does not result in changes in BBB transport of L-DOPA." (PMID 22316420, 2012). "In fact, growth factor-mediated improvement in locomotor capabilities in models of Parkinson's disease and aging can occur with increased TH expression, TH phosphorylation, or DA tissue content strictly in the SN." (PMID 22242182, 2012). "As TH catalyses the formation of L-DOPA, Parkinson's disease can be considered as a TH-deficiency syndrome of the striatum." (PMID 22912680, 2012). "The four candidate genes are ubiquitin B (UBB), septin 5 (SEPT5), G protein-coupled receptor 37 (GPR37) and Tyrosine hydroxylase (TH), all of which have been involved in the Parkinson disease pathway." (PMID 21731658, 2011). "Considering that the previous dystonia panel did not include structural variations of GCH1 and TH and did not exclude variants related to Parkinsonism, we performed WGS to conduct a more detailed investigation." (PMID 40146714, 2025).
Parkinson disease (continued). "We conducted an analysis using a confocal microscope to examine the expression of three neuronal markers that are generally downregulated in Parkinson’s disease patients, glial fibrillary acidic protein (GFAP), tyrosine hydroxylase (TH), and microtubule-associated protein 2 (MAP2)." (PMID 40227236, 2025). "Moreover, cell death in the SNpc, decreased tyrosine hydroxylase levels, and striatal dopamine content, together with the phenotypic characteristics, indicate the onset of the early pre-symptomatic parkinsonism in experimental animals." (PMID 41009423, 2025). "At the same time, a 40–50% decrease in dopamine and TH-positive neurons of SNpc is observed in the animals’ brains, accompanied by impaired gait and the overall neurological decline, indicating the early motor stage of parkinsonism." (PMID 41009423, 2025). "REST enhances TH expression, protects dopaminergic neurons from Mn toxicity, reduces oxidative stress, regulates apoptosis, promotes antioxidants, and its dysfunction links to Parkinson’s and Alzheimer’s disease." (PMID 40278152, 2025). "PFF α-syn mice (non-transgenic model of Parkinson’s disease (PD)) injected with irisin showed improved motor functions, reduced tyrosine hydroxylase activity, loss of dopamine receptors and dopaminergic neurons, and reduced amount of residing α-synuclein." (PMID 39687518, 2024). "In summary, Safranal increased the expression of TH and DA content in Parkinson’s mouse." (PMID 38683404, 2024). "PA-96 supported the survival of cultured naïve dopamine neurons, alleviated motor deficits in MPTP and haloperidol-based mice models of Parkinson’s disease, and increased the density of tyrosine hydroxylase positive neurons and dopamine concentration in the midbrain of an MPTP-damaged brain." (PMID 39339493, 2024). "In addition, AAV-mediated Mst1 expression reduced the loss of TH-positive neurons, ameliorated behavioral deficits, and improved mitochondrial function in an MPTP-induced Parkinson’s disease mouse model." (PMID 38443598, 2024). "An essential interplay between HIF-1 and Parkinson’s disease involves tyrosine hydroxylase (TH)." (PMID 38731800, 2024). "This could be explained by the role of cAMP in positively regulating tyrosine hydroxylase mRNA expression and promoter activity, a pattern also observed in vivo in a Parkinson’s disease mouse model." (PMID 39456033, 2024). "As shown in rat models of aging-related parkinsonism and PD, three indices of DA biosynthesis (DA tissue content, TH protein, and TH phosphorylation) in the SN, but not striatum, are associated with changes in locomotor function." (PMID 38256204, 2024). "Our study found that perilla seed oil, rich in ALA, may enhance DHA synthesis, leading to increased TH protein expression and the potential preservation of dopaminergic neurons, thereby potentially alleviating motor impairments in Parkinson's disease." (PMID 39554352, 2024). "Two weeks pre- and post-treatment with the plant-derived antioxidant curcumin also demonstrated neuroprotective effects in the 6-hydroxydopamine-induced rat model of Parkinson’s disease, specifically by increasing the density of TH-positive neurons in the striatum and SNpc of animals." (PMID 37371945, 2023). "A few studies reported that transcranial photobiomodulation was used to treat Parkinson's disease (PD), the positive effects of which were related to irradiating tyrosine hydroxylase positive (TH +) neurons in the substantia nigra pars compacta (SNc) to improve disabling dyskinesias." (PMID 36814278, 2023). "Post-mortem validation of the Parkinson’s disease model confirmed that intra-MFB 6-OHDA caused significant ablation of TH+ cells in the SNc ipsilateral to the injection with no cell loss in sham rats." (PMID 37100804, 2023). "This study found that intraperitoneal injection of MPTP could significantly reduce TH in the substantia nigra of mice, resulting in Parkinson’s-like symptoms." (PMID 37393274, 2023).
Parkinson disease (continued). "Indeed, PLIN4 is upregulated in a mouse model of multiple sclerosis and Parkinson's disease where it appears to impact tyrosine-hydroxylase (TH)+ dopaminergic neuronal function." (PMID 35031523, 2022). "Some studies have shown that neurotrophic factors such as glial cell-derived neurotrophic factor (GDNF) and brain-derived neurotrophic factor (BDNF) upregulate tyrosine hydroxylase (TH), improve movement disorders and provide neuroprotection in animal models of Parkinson’s disease." (PMID 35557834, 2022). "Tyrosine hydroxylase (TH) is the rate-limiting enzyme for dopamine (DA) synthesis, and a reduction in TH is one of the key pathological changes in the degenerative necrosis of dopaminergic neurons in Parkinson’s disease." (PMID 36678536, 2022). "Our previous study reported that the glucuronomannan oligosaccharide GM2 from Saccharina japonica could ameliorate behavioral deficits and increased the protein level of TH in the striatum of Parkinsonism mice." (PMID 33503975, 2021). "Consistently, Lewy bodies are positive for phosphorylated TH in Parkinson’s disease." (PMID 33429895, 2021). "When a defective herpes simplex virus type 1 vector expressing human TH was delivered into the striatum of 6-hydroxydopamine–lesioned rats used as a model of Parkinson’s disease, long-lasting expression of TH and long-term behavioral recovery were maintained for 1 year." (PMID 34795566, 2021). "Following the Parkinson’s disease animal behavioural assessment by suspension and swim tests, the brain tissue injuries were evaluated by hematoxylin and eosin, TdT-mediated dUTP-biotin nick end labelling, and tyrosine hydroxylase stainings." (PMID 33494069, 2021). "In summary we demonstrate that gene delivery of NRTN can induce long-standing transgene expression in Parkinson’s disease subjects lasting for at least 8–10 years with prominent upregulation of TH in focal areas of the putamen and substantia nigra that express NRTN." (PMID 32203581, 2020). "Loss of TH immunoreactivity also occurs in Parkinson’s disease, although the role of this finding in the pathophysiology of Parkinson’s disease is not defined." (PMID 32977825, 2020). "The restorative effects of supplementation with uridine monophosphate (UMP), DHA, and choline were indicated by increasing striatal dopamine levels and tyrosine hydroxylase (TH) activity, and by enhancing levels of membrane phospholipids and synaptic proteins in a rat model of Parkinson’s disease." (PMID 32839416, 2020). "The reported phenotypic overlap between PD patients with PARKIN mutation and rare forms of dystonia-parkinsonism, such as levodopa-responsive dystonia (DRD), prompts screening for PARKIN mutations along with GTP cyclohydrolase 1 and tyrosine hydroxylase in clinically diagnosed DRD patients." (PMID 30971883, 2019). "TH+ gastric neurons may thus be relevant to understand early pathological events in Parkinson’s disease." (PMID 29031500, 2018). "The results of limited efficacy for the AAV-NRTN trial when injected into putamen, together with findings that four to five years after diagnosis of Parkinson’s disease there are few tyrosine hydroxylase (TH) fibres left in the putamen, led to clinical trials targeting the substantia nigra." (PMID 28208742, 2017). "We used 1-methyl-4-phenyl-1,2,3,6-tetrahydropyridine (MPTP), a neurotoxin that induces Parkinson disease, to evaluate the change of midbrain structure and the behavior of the anti-inflammatory factor e-cadherin, interleukin-6, tyrosine hydroxylase, phosphatase and tensin homolog, and caveolin-1." (PMID 27194825, 2016). "High DA levels in the striatum and hippocampus may support early immune stimulation being an animal model of schizophrenia, however the decreased TH immunoreactivity in the SNpc could be more relevant to the pathogenesis of Parkinson’s disease." (PMID 25602957, 2015). "In the SN of Parkinson's rats, there are fewer TH-ir neurons but more iron-staining cells." (PMID 26146528, 2015).